MYOC (myocilin)
Diseases named in the same sentence as MYOC in open-access papers (continued):
Sharing a sentence is not in itself a finding about the gene and the disease.
glaucoma (continued). "Accumulated abnormal myocilin protein may be toxic towards TM cells and may subsequently evoke their dysfunction or apoptotic cell death, which may eventually result in decreased aqueous outflow, elevated IOP, and subsequent glaucoma development." (PMID 32545285, 2020). "In this sub-group, a stronger effect was observed (P = 1.3x10-8, OR = 0.68) versus those glaucoma cases without a definitive record of POAG (OR = 0.77 [95% CI: 0.67–0.88]), reminiscent of the stronger risk effects seen at the myocilin (MYOC) gene and other established genes in the POAG subgroup." (PMID 32369491, 2020). "Specific genes and their products (e.g., trabecular meshwork-inducible glucocorticoid response protein/myocilin, fibronectin, optineurin, procollagen C-proteinase enhancer 1 (PCOLCE1), cytochrome P450 1B1) found in TM have been shown to play roles in glaucoma pathogenesis." (PMID 20161819, 2010). "Similarly, homozygous transgenic mice expressing mutant myocilin Y423H show reduced secretion of myocilin into the AH, although the animals do not develop glaucoma." (PMID 19023451, 2008). "From our data we can hypothesize that the presence of extracellular mutant myocilin could be required to produce the disease phenotype, offering an explanation for the lack of glaucoma in K423E homozygous patients." (PMID 19023451, 2008). "Similarly, overexpression of the MYOC gene does not induce glaucoma-related phenotypes." (PMID 41227293, 2025). "Myocilin has no known function, and there is no glaucoma phenotype in Myoc knockout mice or in individuals with a homozygous N-terminal truncation mutation or hemizygous deletion of MYOC, but rare non-synonymous coding mutations lead to toxic intracellular sequestration of misfolded myocilin." (PMID 36579626, 2023). "Finally, the absence of OAG phenotype in an elderly woman homozygous for the Arg46Stop mutation along with the absence of glaucoma in people hemizygous for MYOC, suggested that the loss of functional myocilin is not critical for glaucoma development or for normal eye functioning." (PMID 21709622, 2011). "For example, individuals carrying a mutation in their MYOC, OPTN, or other glaucoma Mendelian genes are likely to have early-onset glaucoma (<40 years of age), yet, up to one-fifth of individuals with mutations may not have manifest glaucoma, even in older age." (PMID 40168146, 2025). "Recent studies have investigated transgenic mice homozygous for MYOC and estimated the steady-state level of myocilin in the AH of the mice, demonstrating that mice overexpressing the wild-type myocilin did not develop elevated IOP or glaucoma." (PMID 19287508, 2009). "It was reported that MYOCWT transgenic mice did not exhibit glaucoma phenotypes, so it is speculated that the pathological phenotypes in POAG patients are only correlated with abnormal mutant MYOC proteins." (PMID 38212635, 2024). "While some studies report that myocilin up-regulation is responsible for IOP elevation, other ones report that neither its overexpression nor its haploinsufficiency is the primary mechanism for glaucoma phenotype." (PMID 38152303, 2023). "While the physiological function of WT MYOC remains unclear, several mouse studies employing genetic strategies that either overexpress or disrupt Myoc gene expression did not lead to increased IOP or result in glaucoma." (PMID 40385286, 2025). "The function of MYOC is still not known, however its been reported that MYOC may interact with other olfactomedin knows as optimedin (OLFM3), these wo proteins are expressed in human trabecular meswork and retina, and may be involved in glaucoma disease." (PMID 27821182, 2016).
primary open-angle glaucoma (107 papers, 2007 to 2026). "Myocilin mutations are most associated with open-angle glaucoma, making up around 5% of all hereditary glaucoma cases." (PMID 40458333, 2025). "Missense mutations in the MYOC gene, particularly those affecting the olfactomedin (OLF) domain of the myocilin protein, can be causal for open-angle glaucoma—a leading cause of irreversible blindness." (PMID 40667264, 2025). "In a subset of patients, open-angle glaucoma is linked to genetic factors, namely, a mutation in the myocilin gene that is inherited in an autosomal dominant fashion and is characterized by frequent nucleotide substitutions." (PMID 34802085, 2022). "The glycoprotein myocilin (MYOC) and its associated gene have been extensively studied in open-angle glaucoma, but studies in other cells have rarely been reported." (PMID 34356541, 2021). "Juvenile open-angle glaucoma is a type of open-angle glaucoma that develops before the age of 40 years and can be the result of myocilin (MYOC) mutations." (PMID 33391921, 2020). "In contrast, the myocilin gene (encoding a related protein which is mutated in human open angle glaucoma) had negligible expression in embryo and early neonate but increased expression at neonatal day 16 and in adult eyeball." (PMID 30696701, 2019). "Mutations of optineurin (OPTN) and myocilin (MYOC) genes were associated with the enhanced apoptosis of RGCs in patients with open-angle glaucoma." (PMID 31949441, 2019). "The inherited form of open angle glaucoma arises due to a toxic gain-of-function intracellular misfolding event involving a mutated myocilin olfactomedin domain (OLF)." (PMID 31484937, 2019). "Mutations in myocilin and optineurin are responsible for approximately 5% of primary open angle glaucoma (POAG)." (PMID 22509100, 2012). "Higher levels of myocilin have been related to glucocorticoid-induced ocular hypertension and open-angle glaucoma; however, a putative association between myocilin expression and open-angle glaucoma is still controversial." (PMID 22194647, 2011). "We report a novel mutation (Y371D) in MYOC from a Caucasian family who presented with progressive open-angle glaucoma requiring early trabeculectomy." (PMID 19784393, 2009). "Three previous studies have tested for an association between high myopia and polymorphisms in the open angle glaucoma gene, myocilin (MYOC), all in subjects of Chinese ethnicity." (PMID 19180258, 2009). "Among these candidate genes, Myocilin mutations account for about 3–4% of open angle glaucoma (OAG), with the Gln368Stop nonsense variant accounting for many, but not all, of the adult onset OAG cases." (PMID 17359525, 2007). "In open-angle glaucoma, mutations in the myocilin gene (MYOC) account for 2–4% of cases." (PMID 39457477, 2024). "MYOC/TIGR mutations are associated with some forms of adolescent open-angle glaucoma." (PMID 35865166, 2022). "A database on myocilin genotypes may help clinicians and researchers to identify individuals at risk of developing open-angle glaucoma." (PMID 34802085, 2022). "Genetic studies have linked myocilin with open-angle glaucoma." (PMID 32953253, 2020). "Furthermore, the current evidence suggests that those MYOC gene variants that confer an increased risk of open angle glaucoma are different from those that increase susceptibility to myopia." (PMID 19180258, 2009). "While the exact cause of the disease is not well understood, mutations in the protein myocilin, particularly within the olfactomedin (OLF) domain, have been associated with the development of increased intraocular pressure and open-angle glaucoma." (PMID 40458333, 2025). "Mutations in MYOC, especially those affecting its olfactomedin (OLF) domain, can lead to myocilin-associated open-angle glaucoma (OAG), a prevalent and irreversible form of blindness." (PMID 40667264, 2025).
primary open-angle glaucoma (continued). "More than 20 genetic loci have been linked to primary open angle glaucoma (POAG), which is the major type of disease, but only a few genes have been identified, including MYOC, OPTN and WDR36." (PMID 24752605, 2014). "The authors of the study found only three benign polymorphisms, which were identified in MYOC and OPTN in patients with primary open-angle glaucoma (POAG) and in control subjects." (PMID 22355250, 2012). "Patients affected with primary congenital or open angle glaucoma carrying double heterozygous mutations, one in CYP1B1 and the other in MYOC, have previously been reported in three studies." (PMID 18385784, 2008). "One of the most studied genes involved in the onset of open-angle glaucoma is myocilin (MYOC)." (PMID 38397193, 2024). "The remaining five mutations are found in the intronic region of myocilin and have not been associated so far in any case of open-angle glaucoma." (PMID 21203411, 2010). "The authors suggested that CYP1B1 may act as a modifier locus for MYOC in promoting open angle glaucoma." (PMID 18385784, 2008). "For example, specific genes, such as CYP1B1, which is linked to primary congenital glaucoma, and MYOC, OPTN, and TBK1, which are associated with primary open-angle glaucoma (POAG), are highlighted as critical markers for assessing genetic risk." (PMID 39840199, 2024). "MYOC is the first gene to be linked to juvenile open-angle glaucoma (JOAG) and some forms of adult-onset primary open-angle glaucoma (POAG)." (PMID 21709622, 2011). "Linkage studies of familial and congenital glaucoma have shown the existence of genes with a significant effect on the disease, such as MYOC (myocilin) and OPTN (optineurin) for familial primary open-angle glaucoma (POAG) and CYP1B1 for congenital glaucoma." (PMID 38333055, 2024).
juvenile open angle glaucoma (37 papers, 2008 to 2025). Juvenile glaucoma (JG) is a rare autosomal dominant open angle glaucoma, characterized by early onset, severe elevation of intra ocular pressure of rapid progression, leading to optic nerve excavation and, when untreated, substantial visual impairment. "MYOC variants were discussed in 31 (15.8%) studies with prevalence up to 36% among patients with juvenile open angle glaucoma." (PMID 38386645, 2024). "Pathogenic variants in the Myocilin gene (MYOC) cause juvenile open angle glaucoma (JOAG) in 8–36 % of cases, and display an autosomal dominant inheritance with high penetrance." (PMID 27080696, 2016). "It has been found that mutations in MYOC account for more than 10% of dominant juvenile open-angle glaucoma cases and approximately 3% to 4% of unselected adult onset POAG." (PMID 21677793, 2011). "In our study, MYOC was screened for mutations in the pedigree with juvenile glaucoma with goniodysgenesis." (PMID 19668597, 2009). "MYOC mutations account for most dominant juvenile glaucoma cases and for approximately 2% to 4% of unselected adult onset POAG." (PMID 18728751, 2008). "Consistently, MYOC mutations are linked to juvenile open-angle glaucoma." (PMID 40978119, 2025). "The MYOC gene is associated with juvenile open-angle glaucoma (JOAG)." (PMID 39809167, 2024). "Myocilin mutations account for 8-36% of juvenile open-angle glaucoma and 2-4% of adult-onset POAG." (PMID 33391921, 2020). "The myocilin gene implicated in juvenile open angle glaucoma (JOAG) and in adult-onset primary open angle glaucoma (POAG) was chosen as the potential candidate for screening these cases." (PMID 21031026, 2010). "MYOC mutations are responsible for 2%–4% of POAG cases and 8%–36% of juvenile open-angle glaucoma (JOAG) cases." (PMID 36267417, 2022). "Mutations in the MYOC gene, which encodes myocilin protein, have been linked to increased IOP in juvenile open-angle glaucoma (JOAG) and adult-onset POAG." (PMID 35346303, 2022). "Myocilin (the MYOC gene) was the first protein to be identified and linked to both juvenile open-angle glaucoma (JOAG) and POAG." (PMID 34828408, 2021). "MYOC, specifically, is implicated in approximately 4% of POAG cases, but it is also closely associated with juvenile open-angle glaucoma." (PMID 33396423, 2020). "TG-MYOCY437H mice that overexpress a mutant form of the human myocilin (MYOC) gene mimics human juvenile open-angle glaucoma and is considered a model of POAG." (PMID 23527308, 2013). "They postulate that this connection between CYP1B1 and MYOC may explain the digenic mode of inheritance seen in some cases of juvenile glaucoma." (PMID 34638643, 2021). "In 1997, the myocilin gene (MYOC), formerly referred to as the trabecular meshwork-induced glucocorticoid response protein (TIGR), was mapped to 1q, the locus associated with juvenile open-angle glaucoma." (PMID 19710941, 2009). "They found that MYOC (myocilin), FOXC1 (forkhead box C1), PITX2 (paired like homeodomain 2), and CYP1B1 (cytochrome P450 family 1 subfamily B) are both strongly implicated in juvenile glaucoma and ocular hypertension and highly expressed in TM and ciliary muscle cell types." (PMID 37138096, 2023). "CYP1B1 and MYOC are genetic etiologies for primary congenital glaucoma (PCG) and juvenile open-angle glaucoma (JOAG), respectively, tested by four of the four panels." (PMID 36981008, 2023). "Of particular interest, the myocilin gene (MYOC; OMIM 601652), the first open angle glaucoma gene, was initially reported to interact with CYP1B1 through a digenic mechanism, leading to juvenile open angle glaucoma." (PMID 21850185, 2011). "This study was designed to analyze two candidate genes, myocilin (MYOC) and cytochrome P450 1B1 (CYP1B1), in a Chinese pedigree of juvenile glaucoma with goniodysgenesis." (PMID 19668597, 2009).
ocular hypertension (26 papers, 2007 to 2025). Abnormally high intraocular pressure. "Increased accumulation of fibronectin, collagen IV, collagen VI and myocilin have been implicated in endoplasmic reticulum (ER) stress, ocular hypertension and glaucoma." (PMID 32973273, 2020). "We have previously shown that Tg-MYOCY437H mice develop ocular hypertension starting at 3 months of age and that mutant MYOC-induced ocular hypertension is associated with chronic ER stress." (PMID 33154371, 2020). "A 34-year-old woman with marked ocular hypertension was found to carry Gln368STOP and Thr377Met MYOC mutations." (PMID 23304066, 2012). "Notably, MYOC-null mice fail to develop ocular hypertension, RGC loss, or any other ocular abnormality." (PMID 41227293, 2025). "Next, we examined whether mutant myocilin–induced impaired autophagy in the TM is associated with ocular hypertension in Tg-MYOCY437H mice." (PMID 33539326, 2021). "We infer from the Drosophila model that MYOC-associated ocular hypertension in the human eye may result from aggregation of MYOC and induction of the UPR in trabecular meshwork cells." (PMID 19148291, 2009). "Two mouse models were used: a dexamethasone-induced ocular hypertension and transgenic myocilin mouse." (PMID 37075118, 2023). "In this regard, previous studies on steroid-induced myocilin overexpression excluded its role in both ocular hypertension and endoplasmic reticulum (ER) stress." (PMID 38152303, 2023). "Defective autophagy flux has been recently reported in the myocilin (MYOC) ocular hypertensive mouse model." (PMID 37034386, 2023). "Consistent with this, we showed that reduction of CHOP corrected autophagy and promoted autophagic degradation of mutant myocilin, in addition to rescuing ocular hypertension in Tg-MYOCY437H mice." (PMID 33539326, 2021). "Nine weeks after Ad5.MYOC injection, analysis of retinal wholemounts indicated a prominent loss of RGC in eyes with ocular hypertension." (PMID 34299211, 2021). "Genetic or pharmacological inhibition of autophagy exacerbated intracellular mutant myocilin accumulation and worsened ocular hypertension in Tg-MYOCY437H mice." (PMID 33539326, 2021). "Recently we have shown that ISRIB treatment (previously shown to reduce ER stress) effectively reversed steroid and mutant myocilin induced ocular hypertension." (PMID 34830390, 2021). "Depletion of CHOP enhances recognition and degradation of mutant myocilin by autophagy and rescues ocular hypertension in Tg-MYOCY437H mice." (PMID 33539326, 2021). "It is interesting to note that inhibition of ATF4 rescues both Dex and mutant MYOC-induced ocular hypertension." (PMID 33154371, 2020). "Mutations in MYOC are found in 3.86% of Caucasian patients with POAG, including normal tension glaucoma or ocular hypertension, 3.30% of patients of African descendants including African Americans and black residents in Africa, and 4.44% of Asian patients." (PMID 18776955, 2008). "We next examined whether pharmacological or genetic inhibition of autophagy worsens mutant myocilin–induced ocular hypertension." (PMID 33539326, 2021). "It is not understood why autophagy fails to degrade mutant myocilin and whether autophagy plays a critical role in mutant myocilin–induced ocular hypertension." (PMID 33539326, 2021). "Thus, IVT injection of adenovirus containing specific myocilin mutants generated significant ocular hypertension in the mouse." (PMID 18246028, 2008). "Based upon these considerations, we started a study for identifying myocilin (MYOC) and cytochrome P450, family 1, subfamily B, polypeptide 1 (CYP1B1) mutations in a Spanish population with different clinical forms of familial glaucoma or ocular hypertension (OHT)." (PMID 23922489, 2013). "Remarkably, Chop deletion rescued ocular hypertension in Tg-MYOCY437H mice and prevented TM cell death by promoting autophagic degradation of mutant myocilin." (PMID 33539326, 2021).
ocular hypertension (continued). "Although we did not appear to get a complete knockout of MYOC in the TM tissues of these mice, we decreased the mutant MYOC burden sufficiently to both intervene and prevent mutant MYOC-induced ocular hypertension in mice." (PMID 41210166, 2025). "However, a functional study demonstrated that myocilin was not responsible for steroid-induced ocular hypertension in a mouse model." (PMID 39847376, 2025).
congenital glaucoma (9 papers, 2009 to 2024). "We did not identify pathogenic or likely pathogenic variants in other genes known to cause congenital glaucoma, including rare variants (allele frequency <0.001) in ANGPT1, CPAMD8, CYP1B1, MYOC, LTBP2, PITX2, SVEP1, and TEK." (PMID 36453543, 2022). "Digenic inheritance involving CYP1B1 and MYOC has been reported in early-onset congenital glaucoma and PCG." (PMID 30657791, 2019). "Myocilin (MYOC) is a causative gene for POAG and cytochrome P450, 1B1 (CYP1B1) for congenital glaucoma." (PMID 20142848, 2010).
normal tension glaucoma (7 papers, 2008 to 2021). "We observed expression of seven genes which were previously genetically associated with POAG (included normal tension glaucoma (NTG)), namely APOE, CAV1, EDNRA, MYOC, OPTC and TMCO1." (PMID 23028713, 2012). "Mutations in the myocilin gene (MYOC) at GLC1A primarily cause high-tension glaucoma (HTG), and the optineurin gene (OPTN) at GLC1E appears to contribute to normal-tension glaucoma (NTG)." (PMID 19347049, 2009).